TBC1D22B (TBC1 domain family member 22B)
Description:
May act as a GTPase-activating protein for Rab family protein(s).
Synonyms: C6orf197; FLJ20337; dJ744I24.2
Tractability: PROTAC: ubiquitination databases record sites on it; its protein half-life has been measured.
Gene: Protein-coding gene on chromosome 6 (37,257,772 to 37,332,970, forward strand). Ensembl gene ENSG00000065491.
Subcellular location (Human Protein Atlas): Cytosol; Nucleoplasm
Gene Ontology:
Molecular function: 14-3-3 protein binding; protein binding; GTPase activator activity
Biological process: regulation of cilium assembly
Cellular component: Golgi apparatus
Genetic constraint (gnomAD): Loss-of-function variants: 31 observed, 66.36 expected, observed/expected ratio (o/e) 0.47, 90% interval 0.35 to 0.63. The upper end of that interval is the gene's LOEUF score, 0.63, which puts it in group 2 of 6, group 1 being the genes least tolerant of losing a copy. Missense variants: 456 observed, 635.09 expected, observed/expected ratio (o/e) 0.72, 90% interval 0.66 to 0.78. Synonymous variants: 203 observed, 234.3 expected, observed/expected ratio (o/e) 0.87, 90% interval 0.77 to 0.97.
Homologues: Orthologues: macaque TBC1D22B (99% identical), rabbit TBC1D22B (99% identical), mouse Tbc1d22b (99% identical), rat Tbc1d22b (98% identical), guinea pig TBC1D22B (98% identical), chimpanzee TBC1D22B (97% identical), dog TBC1D22B (95% identical), pig TBC1D22B (95% identical), tropical clawed frog tbc1d22b (83% identical), zebrafish tbc1d22b (70% identical). Paralogues in human: TBC1D22A (62% identical), TBC1D4 (21% identical), TBC1D9B (20% identical), TBC1D1 (20% identical), TBC1D9 (20% identical), TBC1D8 (19% identical), TBC1D8B (19% identical), TBCK (19% identical), RABGAP1 (18% identical), TBC1D16 (18% identical), RABGAP1L (18% identical), TBC1D15 (18% identical), and 33 more.
Diseases named in the same sentence as TBC1D22B in open-access papers:
TBC1D22B is named in the same sentence as 4 diseases in open-access papers, as found by Europe PMC text mining. Sharing a sentence is not in itself a finding about the gene and the disease. The quoted sentences say what the papers report.
breast carcinoma (1 paper, 2025). "TBC1D22B, a Golgi‐localized RabGAP linked to poor prognosis in breast cancer, inhibits ER‐to‐Golgi transport via RAB1B inactivation." (PMID 40878439, 2025). "TBC1D22B is a GTPase‐activating protein (GAP) associated with poor prognosis in breast cancer (BC)." (PMID 40878439, 2025).
cancer (3 papers, 2020 to 2025). A tumor composed of atypical neoplastic, often pleomorphic cells that invade other tissues. "RabGAPs are often promiscuous, and it is plausible that TBC1D22B participates in multiple trafficking steps, potentially coordinating a broader remodeling of cellular logistics in cancer cells." (PMID 40878439, 2025). "TBC1D22B is a GTPase activating protein for Rab protein family, and is found to be over-expressed in many cancers." (PMID 32341752, 2020). "It remains to be determined whether the effects of TBC1D22B on cancer‐relevant phenotypes are exclusively determined by its inactivation of RAB1B function." (PMID 40878439, 2025).
tumor (2 papers, 2020 to 2025). "Future studies are needed to delineate the full spectrum of TBC1D22B substrates and to characterize its impact on unconventional secretion and tumor microenvironment remodeling." (PMID 40878439, 2025). "Given its specificity and tumor‐promoting role, TBC1D22B represents a potential therapeutic target in BC, particularly in aggressive Luminal tumors." (PMID 40878439, 2025). "Imputed SNPs rs34349373 and rs2055272, two intronic variants in TBC1D22B (TBC1 Domain Family Member 22B), a GTPase activating protein for Rab family, were significantly (< 10-6) associated with ERG positive phenotype in any tumor foci." (PMID 32341752, 2020). "Together, these findings establish TBC1D22B as a regulator of ER‐to‐Golgi trafficking via RAB1B and implicate it in oncogenic transcriptional remodeling and tumor growth." (PMID 40878439, 2025).
TBC1D22B also shares sentences with these, for which no sentence is quoted: skin cutaneous melanoma (1 paper).